NPHP1 (nephrocystin 1)
Diseases named in the same sentence as NPHP1 in open-access papers (continued):
Sharing a sentence is not in itself a finding about the gene and the disease.
cystic kidney disease (15 papers, 2005 to 2026). A congenital or acquired kidney disorder characterized by the presence of renal cysts. "Aside from the kidney features, which are commonly classified as NPHP and cystic kidney disease, NPHP1 pathogenic variants cause extrarenal phenotypes, including retinal dystrophy and brain malformations in ∼10% of cases." (PMID 40776899, 2025). "The formation of renal cysts in these kidney organoids carrying NPHP1 loss was successfully recapitulated and supported in the differential gene expression patterns in the transcriptome analysis." (PMID 38989059, 2024). "In a previous study, Nphp1-knockout (KO) mice gradually exhibited and expanded renal cysts at 5 months after birth; however, little is known yet about the molecular mechanisms of how nephrocystin-1 deficiency causes cyst formation in kidneys and leads to ESRD." (PMID 38989059, 2024). "Strikingly, renal cysts were present in only 4/12 patients (33%) with NPHP1 mutations, while hyperechogenicity (7/10; 70%) and abnormal corticomedullary differentiation (3/8; 38%) were reported more frequently compared to the cohort average." (PMID 29974258, 2018). "Loss of NPHP1 is the most frequent genetic cause of pediatric cystic kidney diseases." (PMID 36460631, 2022). "Our results revealed a comprehensive cellular atlas of the NPHP1 mice kidney for the first time and identified a novel subpopulation of NPHP1 renal cyst cells defined by a specific molecular marker." (PMID 37583898, 2023). "Immunofluorescence assays revealed that the PCNA expression in the nuclei of renal cyst cells and dilated tubule cells of NPHP1 mice was slightly increased compared with that in other tubular cells in NPHP1 mice and normal tubular cells in WT mice." (PMID 37583898, 2023). "We performed snRNA-seq on kidney samples from adult WT (wild-type) and NPHP1 mice (12 weeks old), the latter of which had preexisting renal cyst formation." (PMID 37583898, 2023). "Furthermore, the overexpression of NPHP1 rescued the renal cyst formation in these patient-derived hiPSC lines." (PMID 38989059, 2024). "To study whether Niban1 is also expressed in the renal cyst cells of NPHP1 patients, we performed immunohistochemistry and immunofluorescence on paraffin-embedded specimens of kidney biopsy tissue from 3 NPHP1 patients and 3 control patients." (PMID 37583898, 2023). "We concluded that Niban1 is a specific molecular marker of NPHP1 patient renal cyst cells." (PMID 37583898, 2023). "Kidney organoids generated from the hiPSCs lacking NPHP1 formed renal cysts frequently in suspension culture with constant rotation." (PMID 38989059, 2024). "Similar to the findings in NPHP1 mice, Niban1 expression was confined to the renal cyst cells and dilated tubular cells of NPHP1 patients and absent from the uninvolved tubular cells of NPHP1 patients and normal tubular cells of control patients." (PMID 37583898, 2023).
cyst (11 papers, 2010 to 2025). A sac-like closed membranous structure that may be empty or contain fluid or amorphous material. "Because the potential for cyst formation by suspension culture should already be derived from kidney organoids at the adherent culture, we compared the global gene expression pattern of kidney organoids on day 18 between healthy group and NPHP1-deficient group." (PMID 38989059, 2024). "The upregulation of cell cycle-associated genes in epithelial cells from organoids derived from individuals with NPHP1 deficiency and CRISPR-edited hiPSCs has been reported, both of which exhibit primary cilia abnormalities and cyst formation." (PMID 40776899, 2025). "After 1 week in the suspension culture (on day 25), cyst formation was observed in NPH1 patient-derived kidney organoids and NPHP1-deficient kidney organoids." (PMID 38989059, 2024). "We believe that our disease model will be useful in developing a treatment for NPH1, either through gene therapy by supplementing NPHP1 or through drug screening to prevent or stop cyst formation." (PMID 38989059, 2024). "TUNEL assays revealed that a proportion of cyst cells and dilated tubule cells had significantly increased apoptotic nuclei, whereas the remaining tubule cells of NPHP1 mice and all normal tubule cells of WT mice had only a small number of apoptotic nuclei." (PMID 37583898, 2023). "Previous immortal cell models are easy to manipulate and to examine the molecular mechanisms related to NPHP1; however, it is hard to recapitulate the complex tissue organization and degeneration, such as nephrogenesis and cyst formation in kidneys." (PMID 38989059, 2024). "We found that the GEF-H1/RhoA pathway was activated in the kidney of NPHP1 knockout (NPHP1KO) mice and NPHP1 knockdown (NPHP1KD)HK2cells and that it was involved in cyst formation, fibrosis, and inflammation." (PMID 36834937, 2023). "Association of ANKS3with ciliary abnormalities, its interaction with nephronophthisis proteins (NPHP1, NPHP4, NPHP8) and its role in cyst formation have been demonstrated following ANKS3 knockdown in zebrafish." (PMID 26327442, 2015). "Using patient-derived and CRISPR-edited iPSCs, kidney organoids lacking NPHP1 exhibited frequent cyst formation under rotational suspension culture with downregulation of cilia-related genes, where this phenotype was rescued by NPHP1 overexpression." (PMID 41302105, 2025). "To explore the molecular mechanisms of cyst formation in kidney organoids lacking NPHP1, we performed RNA-seq transcriptome experiments." (PMID 38989059, 2024). "Interestingly, LKB1 (STK11) was shown to be part of a ciliary module comprising NPHP1, NEK7, ANKS3 and polycystin-1 that regulates cilia-controlled secretion of CCL2, a chemokine that promotes macrophage recruitment and consequent cyst growth and interstitial inflammation." (PMID 34055783, 2021).
kidney failure (10 papers, 2011 to 2025). An acute or chronic condition that is characterized by the inability of the kidneys to adequately filter the blood. "Analysis of the age of reaching kidney failure showed that patients with non-NPHP1 pathogenic mutations reached kidney failure significantly earlier than those with NPHP1 pathogenic mutation (5.7 years vs. 12.42 years, p < 0.05)." (PMID 36227438, 2023). "Age at disease presentation (11.2 ± 1.94 years) and the development of kidney failure (12.4 ± 2.70 years) were later in children with NPHP1 mutations than those with non-NPHP1 mutations (5.2 ± 2.83 years and 5.7 ± 2.92 years, respectively)." (PMID 36227438, 2023). "Children with NPHP1 pathogenic mutations reached kidney failure at a later age than those with non-NPHP1 mutations." (PMID 36227438, 2023). "In fact, the identification of NPHP1 whole-gene deletions are clinically important and are being recognized as a cause of kidney failure of unknown cause in children and adults." (PMID 40776899, 2025). "While the frequency of non-NPHP1 mutations was less than that of NPHP1 mutations, non-NPHP1 pathogenic mutations were associated with an earlier age of disease presentation and an earlier age of reaching kidney failure, as well as more common extrarenal involvement of the liver, eyes, and bones." (PMID 36227438, 2023). "Homozygous CNV deletions of NPHP1 are a well-defined cause of kidney failure." (PMID 37296294, 2023). "Recent research has identified NPHP1 whole-gene deletions in adult individuals with unexplained kidney failure highlighting that this condition is often underdiagnosed and can lead to adult phenotypes as well as the childhood-onset NPHP phenotypes." (PMID 40776899, 2025). "None of the PTCD patients described to date, including the 16 year old patient carrier of the NPHP1 deletion, presented signs of NPH or renal failure." (PMID 21651769, 2011). "The patient in our case did not develop corticomedullary cysts in the kidneys and experienced renal failure soon after birth, suggesting that the LAMB2 mutations but not the NPHP1 mutations played a decisive role in renal failure in this case." (PMID 27004562, 2016).
Senior-Loken syndrome (9 papers, 2011 to 2025). Senior-Loken syndrome (SLSN) is a very rare autosomal recessive oculo-renal disease characterized by the association of nephronophthisis (NPHP), a chronic kidney disease, with retinal dystrophy. "In our cohort of 17 Korean patients with genetically confirmed Senior-Loken syndrome (SLS), four causative genes were identified: NPHP1 (35.3%), NPHP4 (29.4%), IQCB1 (29.4%), and SDCCAG8 (5.9%)." (PMID 40725491, 2025). "In addition to nephronophthisis 1, the same NPHP1 deletion has also been identified in patients with Senior-Loken syndrome-1 (SLSN1, MIM# 266900) and Joubert syndrome 4 (JBTS4, MIM# 609583) with distinct phenotypes." (PMID 26641089, 2015).
retinal degeneration (8 papers, 2010 to 2025). Degeneration of the retina. "Retinal degeneration occurs when NPHP1 deficiency causes protein mislocalization but stops as normal localization patterns are restored." (PMID 33961633, 2021). "Humans with recessive mutations in NPHP1 and NPHP4 develop NPHP, and some patients develop retinal degeneration." (PMID 36533556, 2022). "In this work, we characterize retinal degeneration in a mouse model of NPHP1 and demonstrate the requirement of NPHP1 for compartmentalized protein localization in photoreceptors." (PMID 33961633, 2021). "Here, we characterize retinal degeneration in a mouse model of NPHP1 and show that NPHP1 is required to prevent infiltration of inner segment plasma membrane proteins into the outer segment during the photoreceptor maturation." (PMID 33961633, 2021). "We further show that Nphp1 genetically interacts with Cep290, another NPHP gene, and that a reduction of Cep290 gene dose results in retinal degeneration that continues until adulthood in Nphp1 mutant mice." (PMID 33961633, 2021). "Our study further shows that reduction of Cep290 gene dose exacerbates protein confinement defects and retinal degeneration in Nphp1 mutants." (PMID 33961633, 2021). "In particular, patients presenting NPHP associated with retinal degeneration more often had causative variants in CEP290 and INPP5E, while those with NPHP but lacking retinal disease had molecular defects in CC2D2A, TMEM67, and NPHP1." (PMID 35238134, 2022). "Apoptosis of photoreceptor cells occurs in mice invalidated for Nphp1, however no kidney phenotype was associated with the retinal degeneration in those mice." (PMID 20856870, 2010). "Strikingly, one of the AHI1 variants they described as a potential modifier for neurological involvement in patients with NPHP1 mutations, p.Arg830Trp, was recently identified as a modifier allele for retinal degeneration in patients with NPHP, independent of a primary NPHP1 mutation." (PMID 20683928, 2010). "NPHP1-related SLS (c.555dup) showed macular atrophy and far peripheral retinal degeneration, while sector RP findings were observed in two individuals of Arab or Jewish descent with NPHP1-related SLS (deletion, exon 14–15 deletion, respectively)." (PMID 40725491, 2025).
end-stage renal disease (7 papers, 2011 to 2024). "Recent studies have demonstrated that renal ciliopathies are largely underdiagnosed, as high rates of NPHP1 pathogenic variants (mostly deletion) have been discovered in adults with chronic kidney disease (CKD)." (PMID 38336713, 2024). "Patients with NPHP1 mutations resulting in end-stage renal disease were aged more than 6 years with a mean age of 12.5 years." (PMID 27004562, 2016). "Three patients with RPGRIP1L gene and NPHP1 gene mutation all had end stage renal failure, suggesting that RPGRIP1L gene and NPHP1 gene mutation may be related to kidney involvement especially end stage kidney disease." (PMID 35858853, 2022). "Moreover, juvenile NPH is a constant feature associated with NPHP1 deletions/mutations, that becomes clinically manifest towards the end of the first or early second decade of life with acute or chronic renal insufficiency." (PMID 21651769, 2011). "NPHP1 (MIM# 607100) mutation causes familial juvenile nephronophthisis type 1, another autosomal recessive disease manifesting as medullary cysts and chronic renal failure, which usually occurs in the first decade of life." (PMID 27004562, 2016). "NPHP1 is the major subtype leading to pediatric end-stage renal disease (ESRD)." (PMID 31096956, 2019).
Renal cyst (6 papers, 2010 to 2025). A fluid filled sac in the kidney. "We subsequently analyzed the distribution of NPHP1 and found that NPHP1 still localized to cilia in the cystic kidneys, similar to the distribution observed in normal kidneys." (PMID 20856870, 2010).
Retinal dystrophy (6 papers, 2011 to 2025). Retinal dystrophy is an abnormality of the retina associated with a hereditary process. "Patients with NPHP1 mutations (n = 6, 35.3%) typically demonstrated RP sine pigmento or retinal dystrophy, maintaining relatively preserved central vision independent of renal deterioration." (PMID 40725491, 2025).
Bardet-Biedl syndrome (4 papers, 2015 to 2022). A ciliopathy with multisystem involvement. "Moreover, a recent study demonstrates that heterozygous NPHP1 deletion CNV in combination with NPHP1 point mutations (SNVs) can lead to Bardet-Biedl syndrome (BBS, MIM# 209900)." (PMID 26641089, 2015).
Senior-Løken syndrome (4 papers, 2018 to 2025). "About one-third of NPHP1 cases are syndromic, often presenting with Senior-Løken syndrome, SLS (retinal degeneration) and Joubert syndrome, JS (cerebellar and oculomotor anomalies)." (PMID 38292052, 2023).
Alport syndrome (3 papers, 2020 to 2024). A rare renal disease characterized by glomerular nephropathy with hematuria progressing to end-stage renal disease (ESRD), frequently associated with sensorineural deafness, and occasionally with ocular anomalies. "We found there were no clinical features of Alport syndrome not only in six probands with c.2858G>T(p.(G953V)) in COL4A5 plus pathogenic variants in other genes (e.g., WT1, ADCK4, NPHP1, TRPC6, COL4A4, and PAX2) but also in another six probands with only the c.2858G>T(p.(G953V)) variant." (PMID 31576025, 2020).
autism spectrum disorder (3 papers, 2014 to 2025). A spectrum of developmental disorders that includes autism, and Asperger syndrome. "Whole-gene deletion of NPHP1 has been associated with both NPHP and neurodevelopmental disorders, including autism spectrum disorder (ASD)." (PMID 40776899, 2025).
Joubert syndrome related disorder (3 papers, 2017 to 2025). "Joubert syndrome-related disorders exhibit clinical heterogeneity due to their various genetic causes, including three genes (CEP290, AHI1/JBTS3, NPHP1/JBTS4) and two loci (JBTS1 and JBTS2)." (PMID 40538625, 2025).
Liver fibrosis (3 papers, 2022 to 2025). "Homozygous NPHP1 possibly modified by heterozygous NPHP4 with early-onset ESKD;Compound heterozygous NPHP3 modified by heterozygous NPHP4 variant with early-onset ESKD and hepatic fibrosis;TTC21B contributes possible modifier alleles to NPHP4." (PMID 37628633, 2023).
retinal disease (3 papers, 2014 to 2023). "The region contains 102 genes of which anaphase promoting complex subunit 1 (ANAPC1), c-mer proto-oncogene tyrosine kinase (MERTK) and nephronophthisis 1 (NPHP1) have been previously associated with retinal disease or retinal function." (PMID 25517981, 2014).
retinitis pigmentosa (3 papers, 2024 to 2025). Retinitis pigmentosa (RP) is an inherited retinal dystrophy leading to progressive loss of the photoreceptors and retinal pigment epithelium and resulting in blindness usually after several decades. "Patients with NPHP1 mutations showed retinitis pigmentosa (RP) sine pigmento and preserved central vision independent of renal deterioration." (PMID 40725491, 2025). "WGS detected previously overlooked SVs, including a partial exon 6 deletion in ABCA4 in patient P433 and a homozygous deletion affecting three genes, including NPHP1, in patient P440, who presented with retinitis pigmentosa and renal disease." (PMID 40926010, 2025). "Patient two had a clinical diagnosis of retinitis pigmentosa and the Invitae kit reported BBS10, CA4, and NPHP1 as VUS; BG reported RCBTB1 and CA4 as VUS." (PMID 38892829, 2024).
congenital nephrotic syndrome (2 papers, 2016 to 2022). "Surprisingly, we found concurrent mutations in both LAMB2 and NPHP1 genes, for the first time in a child with congenital nephrotic syndrome." (PMID 27004562, 2016).
developmental delay (2 papers, 2019 to 2021). "A copy number loss encompassing a similar interval (including MALL, NPHP1, LIMS3, RGPD6, and BUB1) has been reported in ClinVar as a variant of uncertain significance with the phenotype of developmental delay and facial dysmorphisms (SCV000709783.2)." (PMID 33597717, 2021). "However, although some research showed behavioral, psychiatric, and developmental delay phenotypes in cases of 2q13 duplication, few reports have confirmed the relationship between NPHP1 duplication and prenatal short femur." (PMID 31566912, 2019).
Fabry disease (2 papers, 2024). Fabry disease (FD) is a progressive, inherited, multisystemic lysosomal storage disease characterized by specific neurological, cutaneous, renal, cardiovascular, cochleo-vestibular and cerebrovascular manifestations. "Genetic findings that modified the diagnosis in 19 patients included mutations in patients with NPHP (NPHP1 [n = 4], TTC21B [n = 3], ANKS6 [n = 1], NPHP3 [n = 1], NPHP4 [n = 1]), collagenopathies (COL4A5 [n = 7], COL4A3 [n = 1]), and Fabry disease (GLA [n = 1])." (PMID 39363361, 2024).
Joubert syndrome 4 (2 papers, 2022 to 2023). "Only NPHP1 is associated with a phenotypically relevant disease (Joubert syndrome 4) and its contribution to the final PSV score is highest." (PMID 35484572, 2022). "Joubert syndrome 4, the most frequently detected CNV-related chromosomal abnormality in our study, is a rare autosomal recessive disorder involving a ~290 kb homozygous deletion containing NPHP1 in 2q13." (PMID 38201393, 2023).
Kidney Cyst (2 papers, 2018). Abnormal fluid filled sac within the kidney, either acquired or congenital. "Increased echogenicity was a more prevalent finding on renal ultrasound than kidney cysts (65 vs. 43%), especially in patients with mutations in NPHP1 (70 vs. 33%)." (PMID 29974258, 2018).
nephronophthisis type 1 (2 papers, 2010 to 2023). "It has been shown that NPHP4 interacts with NPHP1 (nephrocystin), which is a ciliary protein mutated in nephronophthisis type 1 and which localizes to photoreceptor CC." (PMID 20664800, 2010). "The first discovered and most common is nephronophthisis type 1 (NPHP1) (OMIM #256100), caused by biallelic variants in the NPHP1 gene (often due to a homozygous deletion of the entire gene)." (PMID 38292052, 2023).
nephropathies (2 papers, 2023 to 2024). "With the objective of distinguishing between NPHP1-mutated patients and other nephropathies, we designed a pipeline that considers the problem as a data-driven classification task." (PMID 38336713, 2024). "All patients in this cohort with NPHP1 mutations showed isolated nephropathy, and patients with NPHP1 mutations reported in the past had a probability of isolated nephropathy ranging from 76.5 to 90%." (PMID 36227438, 2023). "Nine children (31%) had NPHP1 mutations, and all presented with isolated nephropathy." (PMID 36227438, 2023). "Additionally, most patients with NPHP1 mutations exhibited isolated nephropathy and less extrarenal involvement." (PMID 36227438, 2023).
Senior-Loken syndrome 1 (2 papers, 2015 to 2024). Any Senior-Loken syndrome in which the cause of the disease is a mutation in the NPHP1 gene. "In both cases, genetic tests were performed which revealed a homozygous whole-gene deletion of NPHP1-encoding nephrocystin-1, providing the unifying diagnosis of Senior-Løken syndrome type 1." (PMID 38433745, 2024).